NEK2 (NIMA related kinase 2)
Diseases named in the same sentence as NEK2 in open-access papers (continued):
Sharing a sentence is not in itself a finding about the gene and the disease.
cancer (continued). "NIMA-related kinase 2 (NEK2) is a type of mitotic kinase involved in tumorigenesis and cancer progression." (PMID 36793341, 2022). "mRNA levels of TTK, NEK2, and CDK1 increased during the development of cancer from stage 1 to stage 4." (PMID 34072728, 2021). "It was reported that NEK2 (NIMA-related kinase 2) is responsible for tumorigenesis, progression, chromosome instability, and drug resistance in cancer." (PMID 34072728, 2021). "These lines of evidence provided the basis for NSC77201 directly regulating activities of TTK, NEK2, and CDK1, which result in antitumor effects in multiple cancer types." (PMID 34072728, 2021). "The objective of the present study was to understand the involvement of four members of the NEK family (NEK1, NEK2, NEK3 and NEK5) in different types of cancers by analyzing differential expression profiles through tissues microarray (TMA) assays." (PMID 31906878, 2020). "We further investigated phosphopeptide signature across five cancer types which led to the prediction of aurora kinase A (AURKA) and kinases-serine/threonine-protein kinase Nek2 (NEK2) as the most activated kinases targets." (PMID 32033228, 2020). "Such confirmation is important in the therapeutic context, as NEK2 and PIM kinases have been shown to be potential targets in therapies in different cancers." (PMID 32504181, 2020). "Significant increases in the protein expression levels of NEK1, NEK2, NEK3 and NEK5, were found in colon and lung in the normal vs. cancer tissues." (PMID 31906878, 2020). "As a member of the NIMA-related kinase family, NIMA-related kinase 2 (NEK2) is a conserved centrosome kinase, with ectopic expression in different kinds of human cancers." (PMID 32190004, 2020). "For example, NEK2 regulated G2/M phases through phosphorylation of HEC1, and HEC1 was crucial for faithful chromosome segregation and high-expression in most cancer cells." (PMID 33109182, 2020). "Overexpression of NEK2 upregulated ABC transporter family members, including ABCB1 (p-glycoprotein, MDR1), the multidrug resistance protein ABCC1 (MRP1), and the breast cancer resistant protein ABCG2 (BCRP)." (PMID 35582716, 2019). "For instance, Nek2 functions downstream of RAS to induce chromosomal instability, a well-established marker of cancer." (PMID 25485281, 2014). "Thus, disruption of the NEK2/HEC1/MAD1 axis can induce mitotic arrest, leading to chromosomal instability in cancer cells." (PMID 41154634, 2025). "In addition to NEK2, which is the most overexpressed NEK in human cancers, including GI cancers, NEK6 overexpression has been reported in various human cancers, making it an attractive target for antitumor therapy." (PMID 40076620, 2025). "This could be in part due to cancer cells containing high baseline levels of free cholesterol, and therefore PEL cells could already be saturated with free cholesterol prior to NEK2 inhibition." (PMID 38592451, 2024). "Considering the refractory nature of PEL to current cancer drugs and the decreased drug resistance signatures we observed in PEL following JH295 treatment, NEK2 inhibition may represent a promising approach for clinical management of this malignancy." (PMID 38592451, 2024). "Moreover, pan-cancer patients with upregulated PLK1, CEP55, FANCI, NEK2, and PTTG1 exhibited a poorer overall survival rate and disease-free survival." (PMID 37274251, 2023).
cancer (continued). "Without a doubt, further research into the roles of Nek2 will improve our understanding of the cell cycle, vertebrate development, and many types of cancer." (PMID 35409400, 2022). "Besides, NEK2-mediated EMT also participated in migration, invasion, and cancer stemness in multiple cancers." (PMID 35705994, 2022). "Although NEK2 has been confirmed as an oncogene, which plays a critical role in a variety of cancers, the functional role of NEK2 in GBM has not been fully elucidated." (PMID 35031599, 2022). "Since cancer models in cell-based systems do not mimic a real tumor microenvironment, a whole animal-based Nek2 overexpression model was needed to understand the complexities of the signaling events." (PMID 35056661, 2022). "So when Nek2 is overabundant or upregulated, it could lead to downregulation of Dsh, thereby directly affecting PCP signaling pathways, such as in malignant tumors." (PMID 35056661, 2022). "Since Nek2 interacts with MAD2 and SAC has emerged as a promising target for cancer therapy, modulation of NEK2 activity and/or MAD2 AS could be exploited therapeutically in TGCTs patients displaying resistance to cisplatin-based chemotherapy." (PMID 34440480, 2021). "We showed that fostamatinib (which can target PLK1 and other over-expressed serine/threonine kinases such as AURKA, MELK, NEK2, and TTK) is more active against cancer lines with more pronounced signatures of invasion (e.g., extracellular matrix organization/degradation)." (PMID 34680307, 2021). "Since Nek2 is not sufficient to initiate tumorigenesis, we asked if it can affect other malignant features of cancer cells." (PMID 33907253, 2021). "Several mitotic kinases, Aurora A, polo-like kinase 1 (PLK1) and NIMA-related kinase 2 (NEK2), were shown to block assembly and induce disassembly of the primary cilium, and upregulated activity of these kinases is frequently found in cancer." (PMID 34207779, 2021). "Although several NEK2 inhibitors and nucleic acid medicines targeting NEK2 have demonstrated preliminary therapeutic effectiveness against cancer cells both in vitro and in vivo, no NEK2 inhibitors have so far undergone clinical trials." (PMID 32504181, 2020). "In addition, NEK2 overexpression is related to poor overall survival for patients with NPC and, promotes cancer cell proliferation by reducing cellular apoptosis." (PMID 32294979, 2020). "Although not identified in each of the five cancer type datasets, yet the enrichment of significant number of downstream target substrates assures probable activation of NEK2 and AURKA across the five cancers." (PMID 32033228, 2020). "Although Nek2 is thought to have a tumour-suppressor function due to its role in the SAC and chromosome stability, it is also oncogenic and drugs are being developed to inhibit its function in cancer therapy." (PMID 29693007, 2018). "Although overexpression of Nek2 failed to induce neoplastic growth, Nek2 does contribute to cancer initiation and progression." (PMID 25485281, 2014). "CKS2 (chr9q22.2), CEP55(chr10q23.33), UHRF1 (chr19p13.3), RRM2 (chr2p25.1), AURKA (chr20q13.2), FLJ39632 (chr14q11.2), FAM83D (chr20q11.23), NEK2 (chr1q32.3) and MAD2L (chr4q27) were all located on PCSRs and showed over-expression in the 9, 8, 10, 9, 8, 9, 9, 8 and 9 types of cancers, respectively." (PMID 24796549, 2014). "Increased gene expression of HOXB7, KIF2C, NEK2, FOXM1 and IGF2BP3 has also been reported for several other types of cancer, suggesting that these genes may be associated with tumor growth in general." (PMID 22879911, 2012).
cancer (continued). "In conclusion, the data presented herein suggest that NEK2 inhibitors may provide a novel approach for increasing the efficacy of FDA-approved CDK4/6 inhibitors in the treatment of aggressive and chromosomally unstable cancers." (PMID 39826695, 2025). "Although CMP3a represented a unique mode of action for sensitizing GSCs with elevated Nek2 levels and presented a promising option for future cancer therapies, it did not have a favorable pharmacokinetic profile (a short half-life), and thus failed to advance in clinical trials." (PMID 35056661, 2022). "NEK2 (never in mitosis gene A-related kinase 2) promotes tumor development through the Wnt signaling pathway, and may be a potential target for cancer treatment." (PMID 33644115, 2021). "Hence, inhibiting Nek2 with small-molecule kinase inhibitors has potential as a novel cancer therapy." (PMID 27833088, 2017). "Besides above reversible compounds, an irreversible inhibitor JH295 with IC50=0.770 μM against NEK2 was reported; however, its antitumor activity against cancer cell lines was not evaluated." (PMID 27764815, 2016). "Although a large number of data demonstrate elevated expression as well as reduced stability of NEK2 in cancer cells, whether NEK2 upregulation plays a role in PCa is not clearly." (PMID 26320076, 2015). "Collectively, these results support the key oncogenic role of NEK2 and suggest that NEK2 targeting approaches represent promising therapeutic tools for TNBC treatment, whose efficacy could be amplified by co-targeting the vulnerability induced by splicing dysregulation in cancer cells." (PMID 35530315, 2022). "Thus, it is tempting to speculate that the upregulation of mitotic kinases, including NEK2 and AURKA, frequently observed in many cancer types results in the gain of a nuclear function that directly or indirectly modulates the transcriptome of cancer cells." (PMID 34930366, 2021). "Nevertheless, additional models, including those overexpressing Nek2 in non-transformed mammary epithelial cells are needed to address whether the acquisition of CA and CIN influences tumor initiation, or contributes to other cancer-associated phenotypes, including invasion and metastasis." (PMID 26512919, 2015). "In addition, we identified that CHEK1 activated NEK2 (data not shown), an established MM CIN marker reported in our previous study, while NEK2 stimulated CIN in cancer cells by regulating CEP250, a core centrosomal protein essential for centriole–centriole cohesion." (PMID 34090465, 2021).
tumor (134 papers, 2008 to 2026). "In CC, NEK2 upregulation is associated with lymph node metastasis, advanced tumor stage, and poor prognosis." (PMID 41256331, 2025). "The overexpression of NEK2 is associated with tumor invasion, advanced stages, and a poor prognosis of CRC." (PMID 40076620, 2025). "The overexpression of NEK2 is observed in all the GI cancers and is associated with tumor proliferation, invasion, drug resistance, and poor survival." (PMID 40076620, 2025). "High expression of NEK2 was associated with vascular invasion and tumor grade in multiple patient cohorts of pancreatic cancer." (PMID 40385396, 2025). "Elevated NEK2 levels have been associated with tumor proliferation, migration, invasion, EMT, stemness, recurrence, drug-resistance, and poor prognosis." (PMID 40076620, 2025). "Using the GEPIA database, we further confirmed the relationship between NEK2 levels and markers of monocytes, tumor-associated macrophages, and M2 macrophages." (PMID 38758909, 2024). "NEK2 elevated levels were positively associated with big tumor mass (P=0.015), higher grades (P=0.002), advanced stages (P=0.013), and distant spread (P=0.004)." (PMID 37600577, 2023). "In LUSC patients, the mutation rate was 53%, in which NEK2 was overexpressed; all of them were significantly related to tumor stage and nodal metastasis status." (PMID 35105934, 2022). "The rate of NEK family gene mutation was high (> 50%) in patients with NSCLC, in which NEK2/4/6/8/ was overexpressed and significantly correlated with tumor stage and nodal metastasis status." (PMID 35105934, 2022). "We further analyzed the associations between protein expression of NEK2 and the clinical pathological features including gender, age, clinical stages, tumor size, lymph node status, survival status, distant metastasis, and treatment by the Chi‐square test." (PMID 30295336, 2019). "NEK2 expression levels are associated with tumor progression and detrimental outcome, as well as with drug resistance." (PMID 29330624, 2018). "Nek2 depletion in a number of tumor cell lines causes growth suppression and apoptosis, while anti-tumor activity has been reported in a range of tumor cell lines following abrogation of Nek2 activity by RNAi depletion alone, or combined with cisplatin." (PMID 27833088, 2017). "NEK2 overexpression is associated with tumorigenensis, tumor progression, drug resistance and predicts poor prognosis." (PMID 27764815, 2016). "The expression level of NEK2 was associated with the clinicopathological characteristics of PCa and tumor recurrence time of PCa patients." (PMID 26320076, 2015). "High expression of Nek2 is implicated in the induction of chromosomal instability, promotion of cell proliferation, and drug resistance in tumor cells as well as a marker for poor clinical outcomes." (PMID 25485281, 2014). "In fact, they were strongly induced by smoking in the early stage tumor tissue and some, e.g., NEK2 and TTK, were also associated with increased mortality risk." (PMID 18297132, 2008). "Taken together, the identified circRNAs and hub genes, as well as the CBT15_circR_28491-miR-139-3p-Kif18a/Cdca8/Nek2 axis, may be closely linked to the thrombotic risk associated with neoplasia and play essential roles in the progression of DVT." (PMID 40662137, 2025). "Notably, NEK2, a cancer‐associated factor linked to tumour progression and treatment resistance, promotes the premesenchymal splicing pattern of TNBC cells by upregulating RBFOX2 expression." (PMID 39243148, 2024). "Additionally, there was a significant correlation between NEK2 gene expression in ccRCC and markers of tumor-associated macrophages, M2 macrophages, monocytes, and dendritic cells." (PMID 38758909, 2024). "Besides, the abnormal expression of NEK2 will cause chromosome instability and aneuploidy, which are the most common phenomena in tumor cells." (PMID 35368696, 2022). "We further explored the mechanism(s) underlying NEK2 mediation of tumor growth." (PMID 33754007, 2021).
tumor (continued). "Due to the complexity of the molecular regulation mechanism in tumor pathogenesis, crosstalk between NEK2 and PKM2 may be caused by different molecular mechanisms in different kinds of tumors." (PMID 34168996, 2021). "NEK2 overexpression activated Akt, an oncogene associated with most malignancies, so NEK2 could be a novel target for suppressing tumor-related pathways." (PMID 34706700, 2021). "TTK, AURKA, BUB1, CDK1 and NEK2 were fundamental kinases with high node degree, which may be required for maintaining the molecular signals underlying tumor progression." (PMID 30598639, 2018). "Overexpression of Nek2 results in premature centrosome separation, which is a cause of chromosome segregation errors, aneuploidy and chromosomal instability, common genetic abnormalities observed in tumor cells." (PMID 27833088, 2017). "Additionally, a high expression of NEK2 may contribute to a suppressive tumor immune microenvironment and is associated with a poor prognosis for patients with GC." (PMID 40076620, 2025). "Furthermore, increased NEK2 overexpression is linked with advanced tumor stage, distant metastases, and lymph node invasion, suggesting that it may be used to predict tumor progression and disease prognosis." (PMID 35880695, 2023). "NIMA - related kinase 2 (NEK2), belonging to the NIMA family, is intricately linked to tumorigenesis and tumor progression." (PMID 41963470, 2026). "Research has demonstrated that NEK2 primarily exerts its tumor-promoting effects by binding to ATP or interacting with HEC1." (PMID 40220284, 2025). "They showed that NCL 00017509 reduces PD-L1 levels by inhibiting NEK2, which enhances T cell function in the tumor microenvironment and sensitizes tumor cells to immune therapy." (PMID 40076620, 2025). "Mechanistically, NEK2 has been shown to activate the Wnt/β-catenin pathway to promote tumor progression and drug resistance." (PMID 40076620, 2025). "The overexpression of NEK2 in ESCC promotes tumor cell migration, invasion, and proliferation and contributes to the radio resistance of ESCC cells." (PMID 40076620, 2025). "The overexpression of NEK2 in GC promotes tumor progression by activating AKT signaling and metabolism and also by regulating ERK/MARK signaling." (PMID 40076620, 2025). "Among these, TAI-95 is the only NEK2 inhibitor undergoing phase 1 clinical trials and has demonstrated favorable oral absorption rates and high accumulation in tumor tissues." (PMID 40220284, 2025). "T‐1101 tosylate, a synthetic compound, induces NEK2 degradation and has shown anti‐tumour activity in HCC and BrC models." (PMID 39243148, 2024). "Data suggests NEK2 contributes to tumor progression by modulating cell proliferation via Ki-67 and Wnt signaling, as well as EMT processes." (PMID 38886738, 2024). "Our animal studies demonstrated that the increase in tumor growth and lung metastasis due to NEK2 overexpression was reduced by the expression of the RhoGDI1 fragment." (PMID 39768163, 2024). "In this regard, multiple preclinical studies have demonstrated that targeting NEK2 can inhibit tumor growth." (PMID 38182898, 2024). "Previous data indicated that NEK2 played a vital role in various biological functions including tumor proliferation, epithelial-mesenchymal transition (EMT), drug resistance, oncogenesis, and immune regulation." (PMID 38783335, 2024). "Transcriptome analysis of samples from the TCGA database and the 2 GEO datasets revealed that NEK2 expression is considerably overexpressed in tumor tissues compared to pa-ra-tumor tissues." (PMID 38758909, 2024). "In this study, we identified the antitumor effects of NEK2 in mediating cell cycle, apoptosis activity, ROS levels, DNA damage, and tumor progression, contributing to radioresistance in ESCC." (PMID 38783335, 2024).